TNF (tumor necrosis factor)
Diseases named in the same sentence as TNF in open-access papers (continued):
Sharing a sentence is not in itself a finding about the gene and the disease.
myocarditis (continued). "Such cytokines are known to induce mitochondrial dysfunction in vitro, and transgenic mice overexpressing IFN-γ in plasma develop a TNF-α dependent myocarditis and cardiomyopathy, which confirm IFN-γ is the culprit in CCC." (PMID 40297326, 2025). "The in vivo results showed that PE inhibited the increased numbers of WBC, Neu, and increased levels of TNF-α and IL-1β in LPS-induced myocarditis rats." (PMID 40642003, 2025). "In drug-induced myocarditis, the TNF-α/IFN-γstorm activates the Nox2–ROS pathway, resulting in a sharp increase in NETosisand triggering microvascular embolism." (PMID 40927089, 2025). "The intersection of LC and myocarditis-related targets was visualized with a Venn diagram, revealing 51 common targets, including TNF, IL1B, IL6, and others." (PMID 41585875, 2025). "Inhibition of TRIM29-PERK signaling pathway can reverse the myocarditis caused by inflammatory cytokines such as IL-6, IL1-β and TNF-α." (PMID 38979420, 2024). "The results show that the most common cytokines to be elevated in the peripheral blood during ICI myocarditis are IL-6 and TNF-α with a surprising minority of patients with IFN-γ elevation and none with IL-1β elevation." (PMID 38785743, 2024). "We found previously that IL-1β levels are increased in the heart of males with myocarditis, while cardiac levels of TNFα are increased in females in our CVB3 model of myocarditis." (PMID 39696682, 2024). "We identified important associations between these myocarditis-like MRI abnormalities and altered immune responses, including increased cytotoxic CD8 T cells, CD4 Th2 cells, TNF-α producing monocytes, and several key inflammatory mediators." (PMID 39073768, 2024). "Key pro-inflammatory mediators like NFκB, TNF-α, and IL-1β are upregulated in mouse models of viral myocarditis and autoimmune myocarditis and play a crucial role in myocarditis progression." (PMID 39273613, 2024). "In infective myocarditis, a cell-mediated and/or humoral inflammatory response with the release of cytokines, TNF, INF, interleukins, other molecules, and antibodies are responsible of cardiomyocytes damage." (PMID 38611673, 2024). "In children with MIS-C and severe myocarditis, These cells show persistent nuclear factor κB (NF-κB) activation, increased TNF-α signalling, decreased expression of NF-κB inhibitors, and a hypoxic response driven by oxidative stress and VEGF signalling." (PMID 39872865, 2024). "Activated NF-κB promotes the transcription and release of proinflammatory mediators such as interleukin-6 (IL-6) and tumor necrosis factor-α (TNF-α), which causes myocardial inflammation." (PMID 37747066, 2023). "Gene ontology analyses identified the upregulation of pathways involved with IL-17, NF-κB, TNF, IL-1β and IL-4 signaling, cell death, and viral life cycle regulators in neutrophils during myocarditis." (PMID 37175422, 2023). "TNF-α, IL-6, and IL-17 secretion by B cells promoted Th1 and Th17 differentiation during myocarditis, while the downregulation of IL-4 significantly limited Th2 differentiation." (PMID 37175422, 2023). "Since the New England Journal of Medicine first published the use of infliximab for fulminant myocarditis after immune checkpoint blockade in 2016, results from 18 patients using TNF-α antibodies for ICI-induced myocarditis have been reported." (PMID 35844550, 2022). "Our work has demonstrated that blood levels of IL-1α, IL-1β, and TNF-α are commonly elevated in myocarditis and, further, that the level of TNF-α is also frequently high in dilated or hypertrophic cardiomyopathy." (PMID 36382160, 2022). "On the other hand, I/R-induced myocardial inflammation is a consequence of the release of inflammatory cytokines including TNF-α from macrophages in the cardiac interstitium as well as peripheral neutrophils which enter the injured myocardium." (PMID 35884777, 2022). "It has been reported that the proinflammatory cytokines IL-1β, IL-6, and TNF-α are increased in acute myocarditis." (PMID 35265721, 2022).
myocarditis (continued). "We next asked what is the real-world usage of TNF-α antibodies in patients with ICI-induced myocarditis." (PMID 35844550, 2022). "High concentrations of TNF-α can reduce myocardial contractile function and induce myocardial dysfunction and myocardial inflammation." (PMID 35529262, 2022). "Before the appearance of high-grade evidence supported by solid clinical trials, guidelines recommended the use of the TNF-α antibody infliximab to treat ICI-induced myocarditis." (PMID 35844550, 2022). "A number of clinical trials revealed that elevated levels of TNF-α, IL-6, IL-8 and other pro-inflammatory cytokines participated in the pathogenesis of cardiac damage during myocarditis." (PMID 34465337, 2021). "Reportedly, selenium markedly increases the expression of miR-128-3p and suppresses the MAPK signaling pathway, which in turn reduces the levels of proinflammatory factors including TNF-α and IL-1 in LPS-induced chicken myocardial inflammation." (PMID 33238881, 2020). "Here, we showed that the intensity of the CD8-enriched myocarditis and electrical abnormalities were related to the concentrations of TNF in the cardiac tissue." (PMID 32194558, 2020). "Increased production of IL-1β and TNF-α in response to CVB3 virus infection induced myocarditis in a mouse model." (PMID 32269577, 2020). "Infliximab, a chimeric monoclonal antibody that binds to TNF-α, has been used to treat patients with steroid-refractory myocarditis and has shown clinical recovery." (PMID 33003425, 2020). "More importantly, our findings place CCL3 as a key chemokine in chronic T. cruzi infection, as a putative sponsor for the CD8+ T-cells and macrophage-enriched myocarditis, in a scenario with abundant IFNγ, TNF and CCL3." (PMID 32194558, 2020). "The mechanisms by which the ASM mediates the TNF-induced hypotension as well as possible direct effects of TNF on the heart, such as myocarditis, which was shown to be lethal in TNF-overexpressing mice, need to be investigated in the future." (PMID 32410851, 2020). "Th17 cells and related cytokines like IL-17A, IL-17F, IL-22, TNF-α are the major regulators of the late or chronic phase of myocarditis, and IL-17A and IL-17F are signature cytokines." (PMID 32269577, 2020). "Cytokines that are elevated in HIV infections and myocarditis include interleukin (IL)-1β, IL-6, IL-8, tumor necrosis factor (TNF), and platelet-derived growth factor (PDGF)." (PMID 29669571, 2018). "These authors showed severe myocarditis in T. cruzi-infected mice, with intense IL-1β and TNF-α production by macrophages and IFN-γ production by CD4+ and CD8+ T cells." (PMID 30364017, 2018). "On day 7, the cardiac IL-1β, TNF-α, IL-6 and IL-17A levels were significantly downregulated in the group of 0.2 and 0.4 mg/kg nicotine compared to the myocarditis group." (PMID 26507386, 2015). "On day 7, the mRNA levels of TNF-α, IL-1β and IL-17A were reduced in the group of 0.1 mg/kg nicotine compared to the myocarditis group." (PMID 26507386, 2015). "Innate immune cytokines such as TNF-α, IL-1β, and IL-6 are essential for the development of acute viral-induced myocarditis." (PMID 26507386, 2015). "Considering that part of the CD8+ cells infiltrating the cardiac tissue play a role in the control of T. cruzi growth, the anti-TNF-induced reduction of myocarditis was expected to have a deleterious result on T. cruzi parasitism." (PMID 25140115, 2014). "The Person correlation analysis showed that on day 7, the TNF-α and IL-6 levels in the myocarditis, nicotine and methyllycaconitine groups were negatively correlated with their corresponding p-STAT3 levels." (PMID 25396421, 2014). "Anti-TNF therapy was shown to reduce the CD8-enriched myocarditis in acute T. cruzi infection in mouse and chronic infection in rats." (PMID 25140115, 2014). "On day 7, the mRNA levels of the IL-6 and TNF-α were significantly lesser in the carvedilol group compared with the myocarditis group (P < 0.05)." (PMID 24225056, 2013).
myocarditis (continued). "On day 7, the mRNA levels of the IL-6 and TNF-α in the myocarditis group were significantly upregulated compared with the normal group." (PMID 24225056, 2013). "Clinical studies have also found increased levels of circulating tumor necrosis factor-α (TNF-α), interleukin (IL)-1β, IL-6 and other pro-inflammatory cytokines in patients with myocarditis." (PMID 23029542, 2012). "Taken together, these data strongly suggest that locally produced myocardial TNF-α played a significant role in the pathogenesis of the myocarditis that was observed selectively in monkeys that received CART." (PMID 21203448, 2010). "Scrub typhus-induced myocarditis involves immune-mediated damage triggered by the host's inflammatory response, including elevated levels of cytokines such as tumor necrosis factor-alpha, interleukin-6, and interleukin-1β, which can induce cardiomyocyte injury." (PMID 40895922, 2025). "In these cases, infliximab (TNF-alpha inhibitor) was used to successfully treat myocarditis." (PMID 41141066, 2025). "A recent paper has shown that the protective effect of TNF-α in myocarditis could be due to its role in promoting activation-induced cell death of autoreactive CD4+ T cells." (PMID 40297326, 2025). "Variance in convalescent TNF-α levels was related to IL-6 variance but was not strongly associated with peak VO2 or with myocardial inflammation." (PMID 39969260, 2025). "The presence of clonal T cells targeting shared antigens across the heart, skeletal muscle, and tumor tissue, along with elevated inflammatory mediators such as IFN-γ and TNF-α, further supports the immune-driven pathogenesis of myocarditis related to ICI therapy." (PMID 41373794, 2025). "While IL-6 and TNF-α have traditionally been at the forefront of inflammatory research in HF, IL-8 has gained attention for its specific contributions to neutrophil-driven myocardial inflammation and tissue damage." (PMID 41210347, 2025). "However, when both LAG-3 and PD-1 were knocked out, a lethal form of myocarditis emerged, characterized by T-cell infiltration, heightened secretion of tumor necrosis factor (TNF), and persistent inhibitory function of Tregs." (PMID 38375475, 2024). "The innate cell release of TNFα, IL-1β and IL-6 as well as complement activation are well documented in viral and autoimmune models of myocarditis, especially in males, where they increase acute and chronic myocarditis." (PMID 38464847, 2024). "Another study suggested that TNF-α may play a role in myocardial dysfunction in a mouse myocarditis model." (PMID 37554366, 2023). "The investigations regarding gender and age disparities in postvaccine myocarditis have revealed that the levels of pro‐inflammatory cytokines such as TNF‐alpha and IFN‐gamma fluctuate between men and women during puberty and then decline later in life, implying hormonal impacts." (PMID 36594165, 2023). "Similarly, 71.4% (5/7) of 7 patients with concurrent ICI-induced myositis and myocarditis who were treated with TNF-α inhibitors died, a value that is higher than 45.5% (5/10) of patients with myocarditis alone." (PMID 35844550, 2022). "However, knockout of both LAG-3 and PD-1 led to the development of lethal myocarditis with T-cell infiltration and increased TNFα secretion but sustained repressive Treg function, emulating trends from human clinical trials." (PMID 36263134, 2022). "Therefore, TNF-α antibodies should be administered to patients with ICI-induced myocarditis with caution." (PMID 35844550, 2022). "Articles using anti-TNF-therapy for ICI-induced myocarditis." (PMID 35844550, 2022). "On the other hand, the high virulent T. cruzi strains induce the upregulation of NLRP3, caspase-1, IL-1β, TNF-α, and iNOS mRNA in heart muscle, compared to low and medium virulent strains, which may contribute to myocarditis and death." (PMID 34336720, 2021).
myocarditis (continued). "Our group had already pointed out that infected and reinfected animals with Colombian strain present a modulation of immune response leading to higher production of proinflammatory cytokines, such as IFN-γ and TNF-α, resulting in marked myocarditis and lower survival rate." (PMID 30622430, 2018). "In the heart of TMEV-induced acute myocarditis, IL-1β with TNF-α could functionally alter lymphatics, while downregulation of lymphatic molecules might contribute to persistent virus infection and inflammation in the CNS of TMEV-IDD." (PMID 30619258, 2018). "Studies have shown that the overwhelming production of pro-inflammatory cytokines (such as TNF-α, IL-1, and IL-6) significantly aggravates myocarditis while inhibiting the expression of the inflammatory cytokines by gene knockout, significantly improving myocardial injury." (PMID 28197102, 2017). "We, then, examined whether anti-TNF therapy influenced the balance of cytotoxic (Pfn+) and inflammatory (IFNγ+) cells composing the chronic T. cruzi-induced myocarditis." (PMID 25140115, 2014). "Actually, IL-10-production by T-cells promotes T. cruzi control and protection from fatal acute myocarditis and, thus, may concur to the beneficial effects of anti-TNF in chronic infection." (PMID 25140115, 2014). "For example, myocarditis can be elicited in susceptible mice by administration of cardiotrophic CVB3 if an additional adjuvant is given through pro-inflammatory cytokines IL-1 and TNF-α." (PMID 25521296, 2014). "Compared to saline-injected mice, anti-TNF-treated mice showed reduced number of Pfn+ cells but similar number of IFNγ+ cells infiltrating the cardiac tissue, supporting that Infliximab remolded chronic T. cruzi-induced myocarditis." (PMID 25140115, 2014). "Patients with confirmed myocarditis have an increased number of infected interstitial cells where proteolytic enzymes or increased concentrations of TNF-α or interleukin may injure the myocytes." (PMID 23782480, 2013). "IL-6 and TNF-α are both involved in the pathogenesis of myocarditis and may induce advanced cardiac dysfunction." (PMID 22761780, 2012). "However, the treatment with anti-GITR resulted in increased mortality, TNF-α production, and myocarditis with enhanced migration of CD4, CD8, and CCR5 leukocytes to the heart in the T. cruzi infected mice." (PMID 22545173, 2012). "Furthermore, myocarditis can be transferred by injection of cardiac myosin-reactive T cells into mice pretreated with TNF-α." (PMID 23675015, 2007). "Thus, TNF-α and IL-1β are involved in the pathogenesis of acute myocarditis and chronic heart disease by increasing inflammation and fibrosis, respectively." (PMID 23675015, 2007). "In parallel with its critical role in inflammation and immune response TNF‐α, especially that produced by cardiac myocytes, can lead to heart diseases including biventricular dilatation, depressed ejection fractions, myocyte apoptosis, myocarditis, fibrosis and atrial thrombosis." (PMID 39264256, 2024). "In the physiopathology of acute myocarditis, inflammation plays a key role characterized by the activation of nuclear factor κB (NF-κB) signaling pathways and the release of pro-inflammatory cytokines, including tumor necrosis factor-alpha (TNF-α) and interleukins (IL): IL-1, IL-6, IL-12, and IL-23." (PMID 39337458, 2024). "Additionally, the role of TNF-α in myocarditis has been deeply investigated." (PMID 37627502, 2023). "Therefore, TNF-α antibodies should be used with caution in patients with ICI-induced myocarditis." (PMID 37304306, 2023). "Therefore, it is important to decrease myocarditis via decreasing expression of inflammatory cytokines (such as IL-1β and TNF-α) and a master transcriptional factor NF-κB that can modulate many genes responsible for both the innate and adaptive immune response." (PMID 26269254, 2015).
myocarditis (continued). "In parallel, myocardial inflammation was induced via nitric oxide production, neutrophil accumulation (myeloperoxidase activity) and activation of the p38-mitogen-activated protein kinase pathway resulting in cytokine release (tumor necrosis factor-alpha, interleukin-6) in control vs. sham animals." (PMID 23663695, 2013). "Consistently with the presence of myocardial inflammation, RT-qPCR analysis showed elevated mRNA levels of IL-1β and IL6 shortly after DEP exposure, with a similar trend for TNFα and the macrophage marker EMR1." (PMID 41444986, 2025). "In CVB3 infection, the expression of interferon beta (IFN-β, gene IFNB1), tumor necrosis factor alpha (TNF-α, gene TNF), interleukin-1 beta (IL-1β, gene IL1B) and interleukin-8 (IL-8, gene CXCL8) are highly upregulated and correlate with myocarditis severity." (PMID 41156753, 2025). "In our study, we showed that TNF-α and IL-6 are elevated in patients presenting with ICI myocarditis but have limited value in prognostication and guiding treatment." (PMID 38785743, 2024). "This review summarizes real-world data from TNF-α inhibitors and other biologic agents for ICI-induced myocarditis to provide more evidence of the efficacy and safety of TNF-α inhibitors and other biologic agents." (PMID 35844550, 2022). "In our cohort, we have demonstrated that infliximab, a chimeric IgG1 monoclonal antibody that blocks tumor necrosis factor-alpha, appears to be an effective and safe agent for steroid-refractory ICI myocarditis." (PMID 33785062, 2021). "The beneficial effect of Met-RANTES on ECG abnormalities and decrease in TNF and CCL3 concentrations in heart paralleled the reduction of myocarditis intensity, mainly due to decrease in the numbers of CD8+ and F4/80+ cells invading the heart tissue." (PMID 32194558, 2020). "Our data demonstrate increased cardiac expression of pro-inflammatory cytokines as shown here exemplarily for TNF-α, IFN-β, IL-6 and IFN-γ in acute myocarditis in both β5i/LMP7+/+ and β5i/LMP7-/- mice." (PMID 21909276, 2011). "We have found that susceptible BALB/c mice have significantly increased levels of the proinflammatory cytokines TNF-α and IL-1β in the heart during acute CB3 myocarditis." (PMID 15550215, 2004). "Distinct from other cardiomyopathies, CCC displays a helper T-cell type 1 (Th1-T) cell–rich myocarditis with abundant interferon-gamma (IFN-γ) and tumor necrosis factor-alpha (TNF-α) and selectively lower levels of mitochondrial energy metabolism enzymes and high-energy phosphates in the heart." (PMID 40297326, 2025). "In our cohort, both TNF-α and IL-6 were elevated during the presentation with ICI myocarditis." (PMID 38785743, 2024). "Elevated inflammatory cytokines (such as TNFα, TGFβ, IL1β, IL-13, IL-4, and VEGF) in MIS-C with severe myocarditis may mediate angiogenesis and vascular homeostasis and enhance cardiac fibroblasts’ development into cardiac myofibroblasts." (PMID 39872865, 2024). "Our study demonstrates that although IL-6 and TNF-α are commonly elevated in patients with ICI myocarditis, they did not significantly predict MACEs or 90-day mortality." (PMID 38785743, 2024). "There was no observed correlation between the histologic grade of myocarditis and the levels of IL-6 and TNF-α (Supplement S2)." (PMID 38785743, 2024). "This suggestion is strengthened as the level of TNF-α expression has been correlated with the degree of cardiac damage from myocarditis regardless of source." (PMID 36851240, 2023). "Another study also revealed that Icariin could downregulate the mRNA levels of TNF-α, ICAM-1, IL-2, and IL-6, which attenuates myocardial inflammation." (PMID 36984421, 2023). "However, the inflammatory M1 polarity genes (IL-1β, IL-6, TNF-α and MCP-1) were significantly increased, with increased rates of myocarditis in the heart of KO mice compared to those of WT mice." (PMID 36982385, 2023).